KRAS (KRas proto-oncogene, GTPase)
Diseases named in the same sentence as KRAS in open-access papers (continued):
Sharing a sentence is not in itself a finding about the gene and the disease.
colon carcinoma (continued). "Notably, we observed that mutations in KRAS, PIK3CA, CREBBP, FAT1, PKHD1, ARID2, and POLE were specifically enriched in right-site colon cancers in both our cohort and the validation cohort." (PMID 36439454, 2022). "Initial reports of KRASG12C inhibition showed that durable responses in mice were dependent on T cells, and a combination of KRASG12C inhibition and anti-PD1 led to improved survival in a subcutaneous tumor model of the genetically engineered G12C KRAS-mutant CT26 colon cancer cell line." (PMID 35857848, 2022). "Found in up to 90% of CRC patients, APC gene inactivating mutations promote the initiation of CRC, whereas KRAS gene mutations have been detected in approximately 40% of CRC patients, seemed to occur during all stages of CRC and were found to mediate colon cancer initiation through CSCs activation." (PMID 35267511, 2022). "To evaluate the effect of Furin repression on the expression of the main Ca2+ regulators previously reported to be involved in colon cancer, we directly analyzed their expression in colon cancer cells with or without KRAS or BRAF mutation." (PMID 35267511, 2022). "Adoptive T-cell therapy targeting mutant KRAS G12D in colon cancer might mediate effective antitumor immunotherapy." (PMID 35359599, 2022). "Activated KRAS significantly increases the uptake of polyamines by colon cancer cells." (PMID 35967333, 2022). "In patients with stage I–III colon cancer, laterality, KRAS mutation and microsatellite instability status were not independently prognostic after curative resection." (PMID 35456940, 2022). "Recently, the EGFR-targeting monoclonal antibody cetuximab has been administered to colon cancer patients without KRAS mutations." (PMID 35110666, 2022). "In addition, we discovered that KRAS was mutually exclusive with LRP1B in the left-sided colon tumors." (PMID 36439454, 2022). "Additionally, KRASG12D, containing the SW480 human colon cancer cell line, was used to investigate the KRAS inhibition of these three molecules." (PMID 35409064, 2022). "We observed strong selection for KRAS-12D over time, which was further enhanced by the EGF receptor inhibitor gefitinib, reflecting the clinical importance of KRAS-12D mutation as a resistance mechanism for anti-EGF receptor therapy in colon cancer." (PMID 36471068, 2022). "In KRAS mutant colon cancer cells, SLC25A22 promotes the accumulation of succinic acid, a metabolite of glutamine in the tricarboxylic acid cycle, which further increases the local methylation degree of DNA and then promotes the activation of Wnt signaling pathway." (PMID 35734400, 2022). "Finally, these two genetic factors follow a unique interaction between two oncogenic pathways by which KRAS increases signaling via the Wnt pathway in colon cancer." (PMID 35409064, 2022). "Mutant KRAS was detected in only one of the DNA types in approximately half of the 30 patients, suggesting that liquid biopsy using evDNA can complement the current widely used patient evaluation methods for colon cancer with a minimal amount of DNA fragments." (PMID 36591510, 2022). "Moreover, we observed a paradox that KRAS has low expression in COAD, but a high level of KRAS is still relevant with poor overall in colon cancer." (PMID 35563733, 2022). "Our study aimed to estimated the incidence of KRAS and NRAS mutations (KRAS exons 2/3/4 and NRAS exons 2/3/4) in Moroccan population, to identify the clinicopathological characteristics of KRAS and NRAS gene mutations and to evaluate their prognosis value in colon cancer." (PMID 33784337, 2021).
colon carcinoma (continued). "Therefore, Caco2 cells, which were highly differentiated colon cancer cells that express wild-type KRAS, were chosen for further assays." (PMID 34954693, 2021). "Baseline expression levels of selected protein targets were investigated by western blot in two BRAFV600E mutant colon cancer cell lines harboring WT KRAS (HT-29 and RKO), two WT BRAF cell lines carrying KRAS mutations (HCT 116 and SW480) and a double WT colon cancer cell line (Caco-2)." (PMID 34201061, 2021). "It was effective against colon cancer cells with either mutant or wild-type KRAS genes." (PMID 34707995, 2021). "In a pooled analysis of resected stage III colon cancer patients receiving adjuvant FOLFOX in the PETACC08 and N0147 trials, BRAF or KRAS mutations were found to be independently associated with a shorter time to recurrence and poorer overall survival in patients with MSS status." (PMID 34063682, 2021). "Indeed, it has been demonstrated that KRAS oncogenic (especially KRASG12V) can induce/up-regulate VEGF in hypoxia via HIF-1-independent mechanisms in colon cancer cells." (PMID 33691728, 2021). "TAK1 has been suggested as mutant KRAS synthetic lethal target in colon cancer." (PMID 33777798, 2021). "Some data suggest the poor efficacy of the available KRAS inhibitors in colon cancer, and Genentech opened two clinical trials of the GDC-6036 compound in combination with one of the following compounds: atezolizumab (NSCLC) or cetuximab, bevacizumab (mCRC), or erlotinib (NSCLC)." (PMID 35141142, 2021). "Together our findings suggest that FTS may trigger stress in SW480 cells, and induce more exosomes secretion as the survival messenger to mitigate the impact of KRAS inhibition in colon cancer cells." (PMID 33466836, 2021). "TAK1 inhibition prompted apoptosis in KRAS-dependent colon cancer cells." (PMID 33777798, 2021). "Furthermore, silencing wild-type and mutant KRAS enhances the resistance to 5-FU in colon cancer cell lines." (PMID 34203665, 2021). "ERN1 knockout KRAS mutant colon cancer cells were screened for genes, of which the inactivation could contribute to a resistance to MEK inhibitors." (PMID 34781949, 2021). "It has been suggested that oncogenic signals such as KRAS may affect HH signaling because both aberrant activation of HH signaling and RAS mutations, are found in colon cancers." (PMID 33691728, 2021). "A mutation in the KRAS gene was detected in the colon tumor: NM_033360.4: c.35G>A, p.(Gly12Asp), but not in the uterine tumor." (PMID 33937060, 2021). "Notably, we observed VHL and ELOB, which are thought to form a protein complex, are top hits that are more essential in KRAS-mutant male colon cancer cells." (PMID 34663427, 2021). "Colon cancers without KRAS and BRAF mutations strongly respond to treatment with cetuximab and are rather resistant to the other three treatments." (PMID 34885128, 2021). "Moreover, these exosomes enhanced the invasiveness of the recipient cells compared to exosomes derived from wild type KRAS-bearing colon cancer cells." (PMID 33466836, 2021). "In addition, the combination downregulated slightly AKT and Wnt/β-catenin signaling pathways in KRAS-mutant colon cancer cells." (PMID 34946546, 2021). "Another study found that the exosomes derived from mutated KRAS-bearing colon cancer promoted the growth of non-transformed cells bearing wild-type KRAS." (PMID 33466836, 2021). "This suggests that KRAS may have undergone a change in isoform distribution when the colon cancer evolved from its primary site (2 T, NM_033360) to the lymph node site (2 M, NM_004985 and XM_011520653)." (PMID 33907296, 2021).
colon carcinoma (continued). "To investigate whether this effect was also detectable in KRAS mutant colon carcinoma cells, we repeated the experiment with LIM1215 and SW948 cells in a slightly modified form." (PMID 33092032, 2020). "We found that colon cancer tissues that had BRAF but not KRAS mutations demonstrated significantly lower concentrations of total ERK, AKT, cyclin d and activated ERK and AKT as compared to Wt." (PMID 33208845, 2020). "Two loci of KRAS (rs121913529 and rs121913530) had prognostic value in patients with colon cancer." (PMID 33254149, 2020). "In multivariable analysis in colon cancers classified as right sided and left sided, we did not identify any statistically significant association between serum lipid profile and KRAS status." (PMID 32594310, 2020). "In the present study, in multivariable analysis in colon cancers classified as right sided and left sided, we did not identify any statistically significant association between serum lipid profile and KRAS status." (PMID 32594310, 2020). "In maximal settings, for patients with left-sided colon cancer and known KRAS/NRAS wild type (WT) molecular status, anti-EGFR antibodies such as cetuximab or panitumumab may be added to chemotherapy doublet, with a moderate-strength recommendation." (PMID 32150483, 2020). "KRAS and BRAF mutational status have been considered as prognostic factors in colon cancers with MSI and may give clues for adjuvant therapy in the future." (PMID 32859214, 2020). "Regulation of RAD51 by MAPKi activity is also observed in KRAS mutant colon cancer cells." (PMID 32719412, 2020). "This systematic review and meta‐analysis of mutation prevalence by tumor location among mCRC patients identified a significant difference in prevalence of both KRAS and BRAF mutations by tumor location, with mutations more frequent among right‐sided colon cancers than left‐sided tumors." (PMID 31856410, 2020). "In a study that included database information from two independent prospective cohort studies (88,691 women and 47,371 men), high vitamin B12 intake was inversely associated with colon cancer, regardless of KRAS status." (PMID 32723394, 2020). "For the BRAF and KRAS biomarkers and the other included prognostic features in the model, no predictive effect for adjuvant chemotherapy has yet been demonstrated in stage II colon cancer patients." (PMID 32458162, 2020). "The importance of ROS in KRAS-mediated tumorigenesis is further corroborated by the fact that the mitochondria-targeted drugs Mito-CP (carboxy proxyl nitroxide) and Mito-Metformin block the proliferation of colon cancer cells." (PMID 31819197, 2020). "In a pooled analysis of PETACC-8 and N0147, and a post hoc analysis of the PETACC-8, both included resected stage III colon cancer patients receiving adjuvant FOLFOX, BRAF or KRAS mutations are independently associated with the decreased DFS in patients with pMMR, but not dMMR tumors." (PMID 33344234, 2020). "For this study, we hypothesized that colon carcinoma cells form TNTs at rates that vary based on KRAS status (wild type vs. mutant) and site of origin (i.e., cells derived from a primary CRC tumor vs. metastatic CRC tumors)." (PMID 31247990, 2019).
colon carcinoma (continued). "However, our results did show that the inhibitory effect of 5‐Aza on MYC, SUZ12, and KRAS is at least partially achieved by miR‐487b in colon cancer cells." (PMID 30791232, 2019). "MC38 (all RAS WT) and CT26 (KRAS G12D) are the only two syngeneic colon cancer cells available." (PMID 31842958, 2019). "We observed a much more enhanced killing effect of the ABT263 + AXIT combination compared with the single drug treatment in HT29 KRAS-mutant cells, suggesting that KRAS-mutant colon cancer cells may be selectively sensitive to the ABT263 + AXIT combination." (PMID 30674639, 2019). "Moreover, a strong association between mutations in APC and other genes such as KRAS or BRAF and colon cancer initiation has in fact been established." (PMID 31142796, 2019). "In addition, a “correction” of ODC overexpression via treatment with indomethacin in colon cancer cells (HCT-116), which carry a mutation in the KRAS gene, was previously reported." (PMID 32256343, 2019). "However, the CI value was less than 0.7 in HT29 colon cancer cells exogenously expressing mutant KRAS." (PMID 30674639, 2019). "Furthermore, AKT and Wnt/β-catenin signaling pathways were slightly down-regulated by the combination in KRAS-mutant colon cancer cells." (PMID 30674639, 2019). "Moreover, ASNS knockdown in vivo suppressed the growth of KRAS-mutant colon cancers, suggesting a tumor-favoring role of the enzyme in these cancers." (PMID 31998641, 2019). "Combined PBR extract and cetuximab acted synergistically against KRAS-mutant colon cancer cells and this synergistic effect could result from β-glucan." (PMID 31717536, 2019). "In several KRAS mutated cancers, the CD44 molecule associates with ALCAM/CD166 promoting an aggressive phenotype that predicts worse outcome and increased risk of liver and lung metastasis (e.g., colon cancer)." (PMID 31552188, 2019). "We hypothesized that tunneling nanotubes (TNTs) provide an additional mechanism of intercellular communication of oncogenic KRAS among colon cancer cells." (PMID 31247990, 2019). "There was one discrepancy in the KRAS gene status between the colon tumor tissue and cfDNA." (PMID 31134762, 2019). "Moreover, both ASNS knock-down and the combined treatment with rapamycin and ASNase inhibited the growth of KRAS-mutant colon cancer xenografts in vivo." (PMID 31998641, 2019). "The primary goal of this study was to compare the performance of the anti-BRAF V600E (VE1) antibody to detect BRAF V600E mutation by IHC in colon cancer cases with/without KRAS mutation." (PMID 29127628, 2019). "In addition, KRAS*G12V over-expression in the human Caco-2 colon cancer cell line significantly promoted DMF-induced cell death, as well as DMF-induced- reactive oxygen species (ROS) formation and -glutathione (GSH) depletion." (PMID 29507676, 2018). "Furthermore, to confirm the inhibitory action of bromelain on colon cancer, we treated KRAS mutant mice (KRASmut/+) with DSS in the absence or presence of bromelain." (PMID 30460115, 2018). "According to previous studies, one of these factors could be KRAS, as its activating mutations were shown to correlate with NOX1 overexpression in human colon cancer samples and in cancer cells." (PMID 29915721, 2018). "KRAS/NRAS/BRAF mutations were not significantly related to patients' age analyzed by Student's t-test or gender analyzed by Chi-square test in colon cancer." (PMID 30416987, 2018). "In this study, we investigated the mutation status of KRAS (exons 2, codon 12/13), NRAS (exons 2/3/4, codon 12/13/59/61/117/146) and BRAF (exons 15, codon 600) in 260 patients, including 86 cases of colon cancer, 140 cases of rectal cancer and 34 cases of gastric cancer." (PMID 30416987, 2018).
colon carcinoma (continued). "Collectively, Src can play a key role in apoptosis induced by the novel EGFR inhibitor MHYs, suggesting that activation of Src might prove effective in treating EGFR/wild-type KRAS colon cancer." (PMID 30158525, 2018). "The current study showed that GSC treatment could suppress KRAS-driven colon cancer both in vitro and in vivo." (PMID 30577618, 2018). "Here we report that the newly synthesized β-phenylacrylic acid derivatives, MHY791 and MHY1036 (MHYs), bind to epidermal growth factor receptor (EGFR) tyrosine kinase domains and function as EGFR inhibitors, having anti-cancer activities selectively in wild-type KRAS colon cancer." (PMID 30158525, 2018). "In addition, KRAS*G12V over-expression in a human colon cancer cell line significantly promoted DMF-induced cell death, ROS formation and GSH depletion." (PMID 29507676, 2018). "To test whether ERN1 is essential in cells with active RAS signaling, we created ERN1 knockout (KO) LoVo, HCT-116, SW480, and DLD1 KRAS mutant colon cancer cells using lentiviral CRISPR-Cas9 vectors." (PMID 30482246, 2018). "Clinical biomarkers shown to be predictive of certain epithelial tumors, such as EGFR or KRAS mutations in colon cancer, are infrequent and/or not predictive of esophageal cancers." (PMID 29507700, 2018). "Vitamin C abrogated cetuximab resistance mediated by mutant KRAS in human colon cancer cells." (PMID 30005692, 2018). "Similarly, the transfer of mutant KRAS proto-oncogene via EVs has been shown to increase the growth of wild-type KRAS-expressing recipient colon cancer cells." (PMID 29760691, 2018). "Finally, we find that ERN1 is an important regulator of JUN activity, which becomes crucial for survival in KRAS mutant colon cancer under conditions of abrogated MAPK signaling." (PMID 30482246, 2018). "We found 10 EGFR mutated NSCLC (6 with short in-frame deletions of exon 19 and 4 cases with single-nucleotide substitutions in exon 21 characterized by the missense mutation p.L858R); and, 7 KRAS mutated colon carcinomas [data not tabled]." (PMID 28099523, 2017). "Moreover, we had 50 PM effusions tested for the EGFR and KRAS mutational analysis based on the previous or contemporary diagnoses of Non Small Cell Lung Cancer (NSCLC) and colon carcinomas." (PMID 28099523, 2017). "Cetuximab, an EGFR antibody, has been approved by the FDA for the treatment of colon cancer with wild-type KRAS, but not those with a KRAS mutation, and for the treatment of certain stages of head and neck cancer." (PMID 28125617, 2017). "Among colon cancers, the v-ki-ras2 Kirsten rat sarcoma viral oncogene homolog (KRAS)-mutated form is notorious for its non-druggable features." (PMID 28800074, 2017). "This enzyme, being the only E2 enzyme, is seen to be sufficient to regulate the overall SUMO status as seen in many instances including a mutant cell model of colon cancer, brain astrocytes, KRAS and invasion of colonic cells by gut pathogens like Salmonella and others." (PMID 28659381, 2017). "Ascorbic acid can abrogate cetuximab resistance in mutant KRAS human colon cancers." (PMID 28800074, 2017). "FTD showed a broad spectrum of anticancer activities against various colon cancer cell lines, irrespective of KRAS or BRAF mutation status, with IC50 values ranging from single to low double‐digit micromolar concentrations." (PMID 28486761, 2017). "As CMS3 colon tumors are characterized by mutated KRAS and since LKB1 mutation also occurs frequently in colon cancer, this mechanism could be a relevant immune escape mechanisms in this context as well." (PMID 29064420, 2017). "HER3 has been involved in intrinsic resistance to MEK inhibition also in KRAS mutant lung and colon cancers and it has been found that MEK inhibition by selumatenib results in MYC-dependent transcriptional up-regulation of HER3, which is responsible for intrinsic drug resistance." (PMID 29312543, 2017).